CD4 (CD4 molecule)
Diseases named in the same sentence as CD4 in open-access papers (continued):
Sharing a sentence is not in itself a finding about the gene and the disease.
asthma (continued). "Here, we characterized the effects of high-fat environment in the fetal period on mice and human cord blood CD4+ T-lymphocytes, and investigated their roles in susceptibility to asthma." (PMID 35745240, 2022). "More specifically, CD4+ T cell responsiveness to allergen exposure correlates well with asthma diagnosis, with associated increases in type 2 cytokines, increased total mucins, and increased MUC5AC in the airways of allergic asthma patients." (PMID 36324676, 2022). "STAT3 is a major regulator of the differentiation and function of Th17 cells, a subset of CD4+ T cells implicated in inflammation in patients with severe asthma." (PMID 35137184, 2022). "A study based on Th2-enriched CD4+ T cells from peripheral blood samples revealed unique and common molecules that are likely to confer pathogenic features to Th2 cells in asthma and rhinitis." (PMID 35246242, 2022). "Among the various subpopulations of CD4+ cells, Th2 cells are most closely associated with the development of asthma." (PMID 36032162, 2022). "The analyses performed on eosinophil and naïve CD4+ T cell samples from the SLSJ cohort have identified several eQTLs for the genetic variants associated with asthma in the discovery cohort." (PMID 35461280, 2022). "Our exploratory study shown that circulating CD4+CCR6+CRTh2+ memory Th2 cells increased in asthma diagnosed children and it was a high-risk factor for asthma." (PMID 34090369, 2021). "Dexamethasone-induced CD4+ FKBP51 expression was associated with worse asthma control in obese participants with asthma." (PMID 34721414, 2021). "Th17 cells, a third subset of CD4+ T-cells, are crucial for the defense of the immune system against fungi and extracellular bacteria and are also implicated in asthma pathogenesis." (PMID 33673725, 2021). "As compared to loose API, circulation CD4+CCR6+CRTh2+ memory Th2 cells had better efficiency in predicting risk of asthma diagnosis based on higher specificity, higher PPV and larger area under the ROC curve." (PMID 34090369, 2021). "This review has focused on the role of human CD4+ T cells in exacerbating asthma phenotypes in the context of 17q12–21 asthma risk SNPs associated with heightened ORMDL3 expression." (PMID 33424845, 2020). "Inflammatory response in asthma is associated with eosinophils, neutrophils, basophils, mast cells, and Th2 lymphocytes (CD4+IL-4+ T cells), which are found in the lungs of asthmatic patients." (PMID 32143368, 2020). "In contrast, Th2 CD4 T cells are associated with promoting strong antibody responses and, in autoinflammatory cases, play a key role in the pathogenesis of asthma." (PMID 31993745, 2020). "As metabolic reprogramming is also intimately linked to CD4+ T cell differentiation and effector function, this link is worth exploring further in the context of asthma." (PMID 33424845, 2020). "CD8 T cells show immunoregulatory/immunosuppressive capacities in a CD4 T cell-associated inflammatory disease such as asthma." (PMID 31156611, 2019). "On the other hand, CD8+ T cells cooperate with CD4+ T cells to promote asthma and have been associated with poor lung fuction and airway obstruction." (PMID 31101830, 2019). "Accordingly, miR-155 was described to stimulate the TH2 response and mucus hypersecretion by directly targeting sphingosine-1-phosphate receptor 1 and cytotoxic T lymphocyte–associated antigen 4 in CD4+ cells in experimental models of asthma." (PMID 31805682, 2019). "Asthma is a chronic airway inflammation associated largely with CD4+ T cells, eosinophils, and mast cells." (PMID 30808413, 2019). "During helminth infection and allergic asthma, naive CD4+ T-cells differentiate into cytokine-producing Type-2 helper (Th2) cells that resolve the infection or induce asthma-associated pathology." (PMID 29700302, 2018). "CRTH2 is expressed on eosinophils, basophils and mast cells as well as Th2-type memory CD4+ T cells and is also known to be associated with the pathogenesis of asthma." (PMID 29507584, 2018).
asthma (continued). "Asthma-induced Brucella susceptibility appears to be dependent on CD4+ T cells, the IL-4/STAT6 signaling pathway and IL-10, and is maintained in IL-12- and IFN-γR-deficient mice." (PMID 30147700, 2018). "In an experimental model of asthma, Wang and Wills-Karp (2011) demonstrated that CD4+/Th2 cells induce lung inflammation associated with IL-17 production in the chronic phase of the disease." (PMID 30233389, 2018). "The activated T cells in the airway wall are associated with inflammation of asthma, and the subsets of T cell antigens have attracted extensive attention by researchers, such as the T cells of CD4+(T helper), CD8+, CD25+, CD28, CD29, CD39+, and CD73." (PMID 30210753, 2018). "Several types of CD4+ T-cells have been implicated in asthma regulation, including Th2, regulatory T, and Natural killer (NK) T cells producing interleukin (IL)-4 and IL-13." (PMID 29422039, 2018). "Above researches pointed out complement activation participated asthma pathogenic processes via regulating CD4+T cells immune responses." (PMID 29123203, 2017). "This is the first study to show that the protective effects of pitavastatin against asthma are associated with CD4+ CD25+ Foxp3+ T cells." (PMID 28729731, 2017). "As severe RSV infection has been associated with an increased risk for developing asthma, it is likely that CD4+T cells have a role in the immune mechanisms involved in asthma." (PMID 29123203, 2017). "Pediatric subjects with asthma had lower expression of hsa-mir-15a in their CD4 T cells, which was associated with higher expression of VEGF-a." (PMID 28362264, 2017). "Different immune cells, such as CD4+ T cells, eosinophils, and dendritic cells (DCs), play a critical role in orchestrating asthma-associated inflammation." (PMID 28974953, 2017). "CD4(+) T-helper 9 (Th9) cells are closely linked to asthma, helping to regulate inflammation and immunity." (PMID 27518187, 2016). "Another report demonstrated that the migration of CD4-positive T cells was decreased in a DPP4 (CD26)-deficient rat model of asthma." (PMID 26975422, 2016). "The three-dimensional (3D) organization of the 17q21 locus in CD4+ T cells was also modified in the asthma-risk alleles to favour recruitment of distal cis-regulatory elements to the ORMDL3 promoter region." (PMID 27848966, 2016). "Th9 cells, a new type of CD4+T lymphocytes, mainly secrete interleukin (IL)-9 and IL-10, which are closely linked with asthma." (PMID 27518187, 2016). "CD4+ T cells showed the greatest increase (threefold) in ORMDL3 expression in individuals carrying the asthma-risk alleles, where ORMDL3 negatively regulated interleukin-2 production." (PMID 27848966, 2016). "We utilized a large data set of H3K27ac ChIP-Seq assays in memory CD4+ T cells to assess effects of asthma-risk genotype on enhancer activity." (PMID 27848966, 2016). "Asthma is closely associated with CD4+/CD8+ imbalance and the use of CD4+ cells as a target point of immune regulation in asthma have been proposed." (PMID 25999796, 2015). "Infiltration of mononuclear cells, mostly CD4 T helper type 2 cells (Th2) and eosinophils, in the airway wall underlines the major pathogenesis of asthma." (PMID 26110056, 2015). "The pathophysiological features of asthma are associated with the presence in the airways of CD4+ T cells and eosinophils, together with goblet cell hyperplasia and mucus hypersecretion, epithelial desquamation and thickening of the submucosa." (PMID 23936192, 2013). "CD11bhigh DCs are known to accumulate in airways adjacent to alveolar spaces after allergen challenge, and have been implicated in the events that define asthma as well as contributing to CD4+ T-cell priming." (PMID 24098126, 2013). "We saw the biggest enrichment (2.11) of asthma-associated SNPs in CD4+ T cells, and we also detected some enrichment of asthma SNPs in liver, adipose nuclei and adipose stem cells." (PMID 23382893, 2013).
asthma (continued). "Using asthma as an example, we document a significant enrichment of asthma-associated SNPs in genomic regions marked by H3K4me1 in CD4+ T cells, which are known to contribute to asthma pathogenesis." (PMID 23382893, 2013). "It was shown that T cells from children with asthma produce less IL-10 mRNA, and severe asthma in adult is associated with reduced frequency of IL-10 producing CD4+ T cells." (PMID 21197090, 2010). "Severity of asthma was associated with increased both serum IgE and frequencies of CD4+/IL-13+ T cells, as well as duration of disease." (PMID 21197090, 2010). "Allergen challenge in subjects with asthma causes a reduction in blood CD4+ T cells and an increase in airway CD4+ cells." (PMID 16393658, 2006). "An experimental study found that CD226 deficiency in CD4 + T cells attenuated airway hyperresponsiveness in asthma in mice, thus validating that targeting CD226 may provide new ideas for the clinical treatment of asthma." (PMID 41573111, 2026). "In the type 2-low asthma model, Sema3E-deficient mice exhibited increased tissue resistance and elastance, accompanied by elevated levels of neutrophils, dendritic cells, CD4 + T cells, and pro-inflammatory cytokines such as IL-17, TNF, IL-1β, CXCL-8, and MCP-1/CCL2." (PMID 40512736, 2025). "The most common asthma variant in children, T2-high asthma, is characterized by atopy, eosinophilic inflammation, elevated Th2 cytokines (IL-4, IL-5, and IL-13), and leukocyte recruitment driven by CD4 + T-cells, mast cells, and eosinophils." (PMID 40806181, 2025). "Polysaccharide A from Bacteroides fragilis has been shown to promote IL-10 secretion by CD4+ T cells, while extracellular polysaccharides from Bifidobacterium longum inhibit Th17 responses in both the gut and lungs, thereby reducing asthma susceptibility." (PMID 40861492, 2025). "Considering that Th2 cells played a pathogenic role in asthma, and that the pathways related to lipid metabolism were enriched in Th2 cells, thus, in this study, we focused on the role of lipid metabolism in CD4+T cells associated with asthma." (PMID 39867638, 2025). "Our results suggest that increased IL-17 and Th2 cytokine production by Hem1-deficient CD4+ T cells may contribute to dermal atopy and asthma, and potentially IBD in Hem1-deficient mice and children." (PMID 40627451, 2025). "Of these, only CD4 cluster 16 was associated with T2 features in both asthma and control groups." (PMID 40965120, 2025). "RhoA‐deficient mice showed a significant reduction in CD4+ T cells and concomitant inhibition of Th2‐differentiation potential, as well as attenuated allergic airway inflammation, pointing out the critical role of RhoA in asthma development." (PMID 41065049, 2025). "In summary CD4+ TRMs are vital pathogenic factors in asthma exacerbation induced by RSV infection." (PMID 39632661, 2024). "CD4+ T cells accumulated in the airway are associated the development of asthma." (PMID 38500102, 2024). "In addition, the frequency of CD103+CD4+ TRM cells in human lung airway tissue was associated with the severity of asthma." (PMID 39193473, 2024). "Research about TES genomic effects (at nanomolar concentrations) on asthma symptoms primarily focuses on airway inflammation since this androgen adversely affects type 2 inflammation that is caused by CD4+ Th2 cells (Th2) and group 2 innate lymphoid cells (ILC2s)." (PMID 36982957, 2023). "Finally, to investigate the functional alterations in Id1‐deficient CD4 T cells in vivo, we used an animal model of asthma." (PMID 37867222, 2023). "Id1‐deficient CD4 T cells ameliorated airway inflammation in an animal model of asthma." (PMID 37867222, 2023). "Recent research has revealed that in obese children with asthma, FKBP51 expression in CD4+ T-Lymphocytes induced by dexamethasone is associated with worsening asthma control, which may underline the occurrence of GCR." (PMID 37986338, 2023).
asthma (continued). "Lastly, Id1‐deficient CD4 T cells ameliorated airway inflammation in an animal model of asthma." (PMID 37867222, 2023). "And the proportion of CCR7+ memory CD4+ T cell was negatively correlated with improved pulmonary tests and significantly associated with disease severity scores and IgE levels, showing significant clinical implications in asthma and eosinophilic inflammation." (PMID 35000593, 2022). "Interleukin-9 (IL-9)-producing CD4+ T helper cells (Th9) have been implicated in allergy/asthma and anti-tumor immunity, yet molecular insights on their differentiation from activated T cells, driven by IL-4 and transforming growth factor-beta (TGF-β), is still lacking." (PMID 36241625, 2022). "The findings suggest that SLIT for asthma patients with SAR-JCP contributed to the further stabilization of asthma symptoms, and changes in peripheral blood CD27-negative CD4+ T cells, γδ T cells, ILC1s, and ILC3s during the off-season were associated with improved asthma symptoms after SLIT." (PMID 35454107, 2022). "Furthermore, this study showed that an increase in the frequency of ILC3s and a decrease in γδ T cells and CD27-negative CD4+T cells during the off-season were associated with an improvement in asthma symptoms in patients with SAR-JCP during the in-season." (PMID 35454107, 2022). "Our findings demonstrate that dexamethasone-induced CD4+ T-lymphocyte FKBP51 expression is associated with worse asthma control in obese children with asthma and may contribute to the unique steroid-resistance observed in this population." (PMID 34721414, 2021). "The significant differences of CD4+ and CD8+ T cells in infants were found between CD and VD groups, which suggested future studies could focus on the role of CD4+ or CD8+ T cells in CD associated wheeze or asthma in early life." (PMID 34970272, 2021). "The unique association of CD4+ T-lymphocyte FKBP51 expression with asthma morbidity among obese participants is consistent with CD4+ T-lymphocytes being central to the pathophysiology of asthma; however, molecular targets are currently limited to those in the Th2 pathway." (PMID 34721414, 2021). "In mice, loss of SOCS2 biases towards CD4+ Th2 differentiation, suggesting patients with allergic diseases such as atopic dermatitis and asthma may benefit from enhanced SOCS2 expression or activity." (PMID 34857742, 2021). "To clarify further the functional importance of upregulation of SERPINB10 expression in Th2 cells, we sorted naïve CD4 T cells from the peripheral blood of asthma patients and transduced them with lentivirus encoding control shRNA or shRNA specific for SERPINB10." (PMID 34126986, 2021). "Thus, novel therapeutic targets for drugs to treat non–Th2-asthma are needed, but the development of such drugs will require elucidation of the mechanism underlying the role of CD4+ T cells in asthma pathogenesis." (PMID 34769255, 2021). "Interestingly, when mice received food allergen-sensitized lymphocytes from CCR9–/– mice, the exacerbation of asthma caused by food allergen CD4+ lymphocytes was eliminated." (PMID 34490243, 2021). "Dexamethasone-induced CD4+ FKBP51 expression is uniquely associated with worse asthma control in obese children with asthma and may underlie the corticosteroid resistance observed in this population." (PMID 34721414, 2021). "Defining the mechanisms by which altered ORMDL3 expression perturbs CD4+ T cell differentiation and function should illuminate new treatment paradigms for patients with 17q12–21 risk SNPs, and expand of our current understanding of asthma pathogenesis." (PMID 33424845, 2020). "Changes in ORMDL3-dependent regulation of the SERCA pump could elicit ER stress and UPR in multiple cell types, including CD4+ T cells, contributing to increased incidence and/or severity of asthma in patients with 17q12–21 risk SNPs." (PMID 33424845, 2020).
asthma (continued). "For example, strong evidence is found for site-specific DNAm as an intermediary via which disease variants regulate ORMDL3, GSDMB, and JAZF1 expression by CD4+ T cells in RA, MS, and asthma, and a similar mechanism in relation to ANKRD55 and IL6ST is limited to RA and MS." (PMID 31945409, 2020). "If this novel hypothesis presents a potential alternative avenue for exploring CD4+ T cell-dependent asthma pathogenesis in patients with 17q12-21 risk SNPs, further detailed characterization of this potential phenotype is required." (PMID 33424845, 2020). "EGR2 has been linked to migration of CD4+ T cells to lung and to blood eosinophil levels in asthma." (PMID 33095769, 2020). "Across the 59 asthma-associated CD4+ T-cell cis-meQTLs, 27 eQTMs comprised 11 unique genes (Table E15), with DNAm a likely regulatory intermediary at 4 of these (DNAm-mediated gene expression was not confirmed at any of 30 similarly identified eQTMs in B cells; Table E18)." (PMID 31945409, 2020). "However, few studies on MDSC subsets and the association between MDSCs and CD4+ T-cell subsets in asthma are reported." (PMID 32549755, 2020). "In this brief review, we focus on growing evidence suggesting that heightened ORMDL3 expression specifically in CD4+ T lymphocytes, the central orchestrators of adaptive immunity, constitutes a major underlying mechanism of asthma pathogenesis by skewing their differentiation and function." (PMID 33424845, 2020). "However, the mechanisms underlying how these CD4+ T cells are regulated in asthma have yet to be fully elucidated." (PMID 30873032, 2019). "In addition to the recent data demonstrating a role in CD4+ T cell function, previous reports have indicated an association with asthma." (PMID 27255083, 2016). "Furthermore, the specialized proresolving mediator maresin-1 has been shown to reduce asthma-associated bronchial inflammation in a murine model, and this was associated with an increased expression of amphiregulin and de novo generation of CD4+ Tregs." (PMID 28066445, 2016). "The aim of this study was to test the hypothesis that variations in allergen-driven CD4 T cell responses are associated with susceptibility to expression of asthma symptoms." (PMID 26922672, 2016). "We noted that the effect of asthma-risk variants on ORMDL3 expression was completely lost when primary naive CD4+ T cells were expanded in culture for a few days, suggesting in vitro expansion per se may dampen the effects of the 17q21 variants." (PMID 27848966, 2016). "These CD4+ T cells produce various cytokines, namely IL-4, IL-9, and IL-13, that may contribute toward the underlying inflammation in asthma." (PMID 28066445, 2016). "Moreover, integrating epigenetic analysis, namely DNA methylation of isolated CD-4+ T cells, across generations will offer the unparalleled opportunity to investigate underlying mechanisms of asthma development in an unique way." (PMID 26637409, 2015). "Finally, since in asthma the Foxp3 expression is specifically associated with CD4+CD25+ T-cells, we investigated the Foxp3 expression in T-cells with this specific phenotype." (PMID 23573194, 2013). "IL-13 was primarily produced by Th2 CD4+ T cells after allergen irritation, and it may induce the entire pathogenic pathway of asthma independently of traditional cells, such as mast cells and eosinophils." (PMID 23382814, 2013). "Finally, we observed that the percentage of CD4+IL-17+ T cells in peripheral blood of patients was associated with the severity of asthma, confirming observations described by other groups." (PMID 23822853, 2013). "Thus, our results clearly show that in vivo primed CD4+ T cells from DO11.10 transgenic mice can be used to induce the hallmark features of asthma in mice." (PMID 22014099, 2011).